RN7SKP101 (RN7SK pseudogene 101)
Gene: Miscellaneous RNA gene on chromosome 15 (46,720,193 to 46,720,512, reverse strand). Ensembl gene ENSG00000223308.
Homologues: Orthologues: chimpanzee 7SK (92% identical), guinea pig 7SK (53% identical). Paralogues in human: RN7SKP176 (68% identical), RN7SKP47 (67% identical), RN7SKP77 (66% identical), RN7SKP86 (66% identical), RN7SKP149 (66% identical), RN7SKP180 (66% identical), 7SK (65% identical), RN7SKP222 (65% identical), RN7SKP246 (65% identical), RN7SKP174 (65% identical), RN7SKP294 (65% identical), RN7SKP78 (65% identical), and 284 more.